AVP (arginine vasopressin)
Diseases named in the same sentence as AVP in open-access papers (continued):
Sharing a sentence is not in itself a finding about the gene and the disease.
Hypertension (55 papers, 2010 to 2026). The presence of chronic increased pressure in the systemic arterial system. "Myocardial infarction, hypertension and cardiovascular shock are associated with an increased secretion of AVP and altered responsiveness of the cardiovascular system to its action." (PMID 36430892, 2022). "Angiotensin II affects the central nervous system by increasing the secretion of vasopressins, such as antidiuretic hormone, arginine vasopressin, and argipressin, which all cause high blood pressure." (PMID 32325920, 2020). "In cystic renal diseases, AVP-mediated stimulation at these sites result in hypertension and associated cardiovascular disease (such as concentric cardiac hypertrophy and diastolic impairment)." (PMID 30601830, 2019). "It has been observed that high levels of fasting AVP is a risk factor for type 2 diabetes and is associated with metabolic syndrome components (obesity, insulin resistance and hypertension)." (PMID 31405072, 2019). "According to Van Kempen and colleagues, the administration of AVP to mice stimulates oxidative stress and causes hypertension, which increases the levels of SSAO." (PMID 27699080, 2016). "Knockdown of PRR in the SON was associated with attenuation of hypertension and a decrease in plasma AVP in SHR." (PMID 23316344, 2012). "End-organ-targeted pharmacological interventions, such as tolvaptan, have demonstrated benefit against AVP-mediated fluid retention, but remain insufficient to address the full spectrum of PD-related complications linked to AVP, including hypertension and immune dysregulation." (PMID 41157262, 2025). "Arginine is essential for producing arginine-vasopressin, which may contribute to symptoms such as hypertension and hyperglycemia associated with glucagon production." (PMID 39707182, 2024). "It has been observed that a chronic AVP increase in the elderly may worsen some diseases, such as hypertension and heart failure, and may increase the risk of thromboembolic events." (PMID 31405072, 2019). "In particular, according to Share and Crofton, for AVP to contribute to hypertension, the pressor responsiveness to it must be sufficiently high, which implies both increased vascular smooth muscle cell reactivity and impaired baroreceptor activity." (PMID 38982989, 2024). "They believed that when GABAergic inhibition converts to excitation, the baroreflex loses its function in buffering BP and instead contributes to the development of hypertension via promoting AVP release." (PMID 39323755, 2024). "Distinctly, some researchers found that suppressing GABAergic excitation inhibits salt-induced hypertension via reducing the output of AVP neurons." (PMID 39323755, 2024). "Given the inhibitory effect of GABA on neurons, it follows that activating the GABAergic system should inhibit the release of AVP from AVP neurons to attenuate hypertension." (PMID 39323755, 2024). "Arginin-vasopressin (AVP), a key player in water metabolism, has been evoked in hypertension development since the 1980s, but, to date, the matter is still controversial." (PMID 38982989, 2024). "To explore this, we compared the expression of hypertension-related genes including AVP, AT1R, and FOSL1, along with the oxidative stress marker mtROS, in the PVN between SPS and control rats." (PMID 39594564, 2024). "A possible role for AVP in hypertension development has been evoked since the 1980s, but, to date, is still controversial." (PMID 38982989, 2024). "Hypertension induced by arginine vasopressin (AVP) is characterized by low circulating renin-angiotensin system activity, which is also found in PE compared to normotensive pregnant women [23••]." (PMID 37043097, 2023). "Despite at least four decades of extensive research, the role of arginine-vasopressin (known as antidiuretic hormone, ADH) and water balance dysregulation in the development and maintenance of arterial hypertension remains controversial." (PMID 35722114, 2022).
Hypertension (continued). "Functional studies are needed to evaluate the extent of the orexin system's contribution to sympathetic activity, increased AVP, and hypertension." (PMID 34702886, 2021). "Further, orexin signaling in the paraventricular nucleus appears critical for the onset and maintenance of hypertension via arginine vasopressin (AVP) upregulation in the DOCA-salt model of hypertension." (PMID 34702886, 2021). "In experimental models of arterial hypertension, AVP content and its gene expression are elevated in the PVN, SON, and NTS." (PMID 34768894, 2021). "Upon binding with OX1R in the PVN, AVP production is stimulated, ultimately leading to the development of hypertension through numerous downstream physiological responses (vasoconstriction, fluid reabsorption, etc.)." (PMID 33633591, 2021). "Between the years 1996 and 2003, animal experiments and clinical studies revealed the adverse effects of elevated AVP on kidney diseases, albuminuria and hypertension." (PMID 32210168, 2020). "The SHRs is known for overactivated sympathetic activity even before hypertension development; thus, several increased in FC in AVP mRNA expression in chronic exposure to salt diet is considered as an estimated outcome." (PMID 32175184, 2020). "Experimental and clinical studies have provided evidence that blood AVP concentration is significantly elevated in hypertension and in patients with post-infarct cardiac failure [282••, 283•]." (PMID 29556787, 2018). "As such, this study compared the responses elicited by AII, AVP, and 5-HT in OAs isolated from sham-operated rats and those with 2K-1C hypertension." (PMID 25140254, 2014). "In addition, according to previous studies, we expected to observe activation of key neuroendocrine stress pathways – including the HPA axis, the sympathetic nervous system, and AVP signaling – as well as the development of hypertension in PVN-BDNF rats." (PMID 41422153, 2025). "Arginine is critical for producing arginine-vasopressin, which may contribute to hypertension in DKA due to overexpression of counter-regulatory hormones." (PMID 39707182, 2024). "Recent data obtained in rats also demonstrate that estradiol prevents salt-dependent hypertension by suppressing salt-induced GABA-ergic excitation in AVP-secreting neurons, resulting in AVP secretion that plays a crucial role in the development and maintenance of hypertension in these animals." (PMID 38982989, 2024). "The role of AVP in hypertension development has long been debated." (PMID 38982989, 2024). "We hypothesized that kinin B1R contributes to hypertension via upregulation of brain orexin-arginine vasopressin signaling." (PMID 34702886, 2021). "Thus, in the present study, we investigated if kinin B1R contributes to hypertension via upregulating the orexin-AVP signaling in the brain." (PMID 34702886, 2021). "This suggests that further investigation of these mechanisms may uncover multiple therapeutic targets to reduce sympathetic activity and AVP release in hypertension." (PMID 33066544, 2020). "Interestingly, high salt intake causes an increase of chloride levels ([Cl−]i) levels in AVP releasing neurons (involving a decrease of KCC2 and an activation of NKCC1), excitatory actions of GABA and AVP dependent hypertension." (PMID 30186114, 2018). "Importantly, the interaction of Ang II and AVP is significantly enhanced in hypertension, post-infarct cardiac failure, and during chronic stress [137•, 145•, 331•, 332•, 333•, 334•]." (PMID 29556787, 2018). "In fact older studies have already suggested that AVP may have a role in development of hypertension." (PMID 28638629, 2017). "Several lines of evidence support a role for AVP in the pathogenesis of hypertension." (PMID 24375010, 2014). "The aim of this study was to test the hypothesis that serum copeptin (a surrogate marker of AVP) is increased in adolescents with essential hypertension." (PMID 24375010, 2014).
Hypertension (continued). "A study of the role of AVP for the development of hypertension after constriction of the abdominal aorta proximal to the renal arteries concluded that AVP plays an important role in the development of hypertension and that the action is mediated via the vascular AVP-receptor (AVPR1B)." (PMID 24174980, 2013). "Previous research has reported that AVP may contribute to hypertension through several pathways, including sympathetic excitation mediated by vasopressin receptors (V1a receptors) in the PVN region, brain RAS hyperactivity via V2 receptors, and peripheral vasoconstriction induced by V1 receptors." (PMID 41543628, 2026). "Pharmacological blockade of kinin B1R could prove to be a valuable new tool in the control of neurogenic hypertension, particularly in patients with refractory hypertension by decreasing circulating AVP, downregulating the orexin A system, and decreasing neuroinflammation." (PMID 34702886, 2021). "Thus, AVP is involved in thermoregulation, cooling operating via activation of a non-selective cationic channel in AVP hypothalamic releasing neurons and in response to hyperosmotic stress with high-salt diets induce or exacerbate hypertension." (PMID 30186114, 2018). "Therefore, reduction in the BRS might lead to increased release of arginine vasopressin and induce hypertension." (PMID 25036025, 2014). "Salt loading enhances AVP neuronal activity and elevates plasma AVP, while PVN vasopressin receptor blockade reduces salt-induced sympathetic excitation and hypertension." (PMID 41543628, 2026). "This heightened orexin activity then stimulates increased production of AVP within the PVN, and subsequent release to peripheral circulation, ultimately leading to the development of hypertension." (PMID 33633591, 2021). "Human renin and AGT double transgenic mice exhibit Ang II-dependent hypertension, which can be attenuated by AVP antagonist suggesting an interaction between the brain RAS and AVP in hypertension." (PMID 23316344, 2012). "Finally, since this is a noninterventional study, the associations we have pointed out allow us only to speculate about the potential role of AVP in BP regulation, but not to establish a causality link between the AVP-induced changes in HA metabolism and the predisposition to hypertension." (PMID 38982989, 2024). "Given the PVN’s involvement in stress responses, PTSD-induced anxiety may alter the expression of genes involved in BP regulation, such as AVP and AT1R, and elevate oxidative stress within the PVN, potentially contributing to hypertension." (PMID 39594564, 2024). "Indeed, microinjection of AVP elicits a similar increase in sympathetic outflow, while antagonism of the V1 receptor in the PVN attenuates SNA outflow and hypertension in high-salt intake rats." (PMID 33633591, 2021). "In addition, in a variety of rat models of hypertension, including spontaneously hypertensive and DOCA-salt sensitive rats, higher levels of AVP in urine and plasma, as well as increased pressor responsiveness to AVP, have been described." (PMID 38982989, 2024). "The lack of consensus on the role of vasopressin in essential hypertension may be the result of the fact that AVP is an unstable molecule both in vivo and ex vivo." (PMID 24375010, 2014). "The levels of vasoactive peptides such as angiotensin II (Ang II), endothelin (ET-1) and arginine vasopressin (AVP), as well as growth factors that have been reported to be augmented in various models of hypertension, may be responsible for the enhanced expression of Giα proteins in hypertension." (PMID 22043206, 2010).
Hypernatremia (46 papers, 2008 to 2026). An abnormally increased sodium concentration in the blood. "In contrast, sodium overconsumption causes hypervolemic hypernatremia, elevated plasma AVP concentration and blood pressure." (PMID 32200401, 2020). "A decrease in plasma AVP levels causes the hallmarks of DI: polyuria (urine outputs>4ml/kg/hour), hypernatremia, dehydration, and hypotension." (PMID 28926566, 2017). "The adaptation of the “healthy organism” to chronic hypernatremia has further been investigated in the HS model with aggressive alterations in the measured parameters and lacking the compensatory mechanisms that had been developed in the AVP-deficient rats throughout the ontogenesis." (PMID 32200401, 2020). "Other findings, such as loss of signal in the posterior pituitary on T1‐weighted MRI, low plasma AVP concentration despite hypernatremia, and failure of urine osmolality to exceed 300 mOsm/L after water restriction, led to the diagnosis of partial CDI." (PMID 40821911, 2025). "The patient exhibited hypotonic polyuria, hypernatremia, elevated serum osmolality, and low plasma arginine vasopressin (AVP) levels within the first week of life." (PMID 40809652, 2025). "In response to hypernatremia or hypovolemia, arginine vasopressin (AVP) is released from the posterior pituitary gland." (PMID 35126177, 2021). "It probably had DI due to the undetectable AVP levels and hypernatremia resulting from short-term water deprivation required for several evaluations." (PMID 34031474, 2021). "As oxytocin regulates natriuresis and AVP regulates water conservation by the kidneys as well as increases blood pressure, both hormones substantially control the hypernatremia-evoked responses." (PMID 32200401, 2020). "He continued to have very low levels of arginine vasopressin (AVP, 1.47 pg/mL) and exhibited hypernatremia (146.1 mmol/L) and persistent strong thirst." (PMID 32460754, 2020). "The regulation of choroidal AVP synthesis is similar to that observed in the hypothalamus and it has been shown that chronic hypernatremia increases the expression of AVP in the CP." (PMID 21349151, 2011). "Inflammatory responses may directly influence kidney function and AVP activity, playing a central role in the development of both hypernatremia and CDI in diabetic patients." (PMID 41211065, 2025). "It should be noted, that the hypernatremia observed in the high salt‐fed CDNOS1KO mouse may also be a consequence of changes to arginine vasopressin and/or resetting of the osmostat as has been reported with mild hypernatremia." (PMID 34665521, 2021). "PrRP is involved in various functions challenged by hypernatremia, like the cardiovascular regulation and the control of oxytocin (promotes sodium excretion) and vasopressin (AVP, stimulates water retention) release from the magnocellular cells of the SON and PVN." (PMID 32200401, 2020). "Under the condition of hypernatremia and hypovolemia,AVP is released and induces AQP2 expression and translocation from intracellularvesicles to the apical membrane in the renal collecting ducts via theV2 receptor to allow water reabsorption and the maintenance of body-waterhomeostasis." (PMID 29718707, 2018). "Moreover chronic dehydration, salt loading and hypernatremia also characteristically upregulate AVP expression in the hypothalamic-pituitary axis and choroid plexus." (PMID 20707896, 2010). "A water deprivation test was performed, and when the bodyweight decreased by 3%, hypernatremia and increased serum osmolality were observed, but urinary osmolality remained low and antidiuretic hormone was low relative to serum osmolality, consistent with an arginine vasopressin abnormality." (PMID 39726668, 2025). "Osmoreceptors in the hypothalamus detect changes in blood osmolality that arise, for example, from hypernatremia and hypovolemia, and induce the release of the peptide hormone AVP (antidiuretic hormone)." (PMID 26903868, 2016).
Hypernatremia (continued). "The key hormone that regulates reabsorption is the antidiuretic hormone arginine vasopressin (AVP), which is secreted by the posterior pituitary in response to hypovolemia or hypernatremia." (PMID 18489790, 2008). "Hypernatremia frequently manifests early post-SAH, and may result from hypothalamic dysfunction, which impairs arginine vasopressin secretion." (PMID 41602996, 2026). "Participation of AVP in the regulation of thirst is indirectly supported by studies on patients with the syndrome of inappropriate secretion of ADH (SIADH) and in patients with adipsic hypernatremia." (PMID 40869169, 2025). "Opposite pathology is observed in patients with adipsic hypernatremia in whom water intake and AVP secretion are not sufficient enough to reduce sodium levels to normonatremic values." (PMID 40869169, 2025). "Regarding the known cooperation between NE and PrRP in the AVP and ACTH release, as well as in habituation to chronic stress, we assume that PrRP acts synergistically with NE in the different responses to chronic hypernatremia." (PMID 32200401, 2020). "In CDI, impaired or absent secretion of arginine vasopressin (AVP) from the posterior pituitary leads to an inability to concentrate urine, necessitating lifelong replacement with desmopressin to prevent dehydration and hypernatremia." (PMID 41153850, 2025). "Taken together, the closely fitted responses of CWI, AVP, sodium concentration, and serum osmolarity indicate that our model captures all of the important apparent features of the human response to acute hypernatremia, which has not been successfully replicated before." (PMID 27899683, 2016).